CRP (C-reactive protein)
Diseases named in the same sentence as CRP in open-access papers (continued):
Sharing a sentence is not in itself a finding about the gene and the disease.
bacterial infection (continued). "Many bacterial diseases are characterized by elevated levels of circulating IL-1β and IL-6 with a concomitant increase in plasma CRP, explaining the good correlation between plasma levels of IL-6 and CRP." (PMID 27977798, 2016). "CRP values above 60–80mg/L within 24 hours of hospitalization are highly sensitive and specific for the diagnosis of a bacterial infection in older people." (PMID 26937636, 2016). "The maximum C-reactive protein (CRP) values in the patients ranged from approximately 5 to 100 mg/L with the majority below 50 mg/L, indicating that severe bacterial infections were unlikely." (PMID 27171557, 2016). "Our selection for a single virus only with an unlikely typical bacterial infection is largely dependent on CRP-levels, which are frequently tested in clinical settings and used to help differentiate between viral and bacterial infections." (PMID 26964038, 2016). "Bacterial infection, inflammation, thrombosis, and necrosis all increase serum C-reactive protein (CRP)." (PMID 27375905, 2016). "SAP, a homologue of CRP, has also been shown to have a protective role against bacterial infections." (PMID 27557501, 2016). "This study found that, the positive rate of PCT in the bacterial infection rate was much higher than that of CRP and WBC, and the difference had statistical significance (P<0.05)." (PMID 28083019, 2016). "An elevated CRP level is considered indicative of a bacterial infection, making distinct stool diagnostics more likely." (PMID 27603141, 2016). "In a recent study CRP was found to be a useful biomarker for distinguishing between viral and bacterial infections in febrile patients in the Mekong." (PMID 27386859, 2016). "The combination of IL-6 and CRP plasma biomarkers can even be used to predict serious bacterial infections in young febrile infants." (PMID 27977798, 2016). "A previous meta-analysis reported that procalcitonin levels are more accurate markers for bacterial infections than CRP levels, while the usefulness of perioperative CRP monitoring in general surgery is generally accepted." (PMID 25888882, 2015). "CRP is present only in trace amounts in healthy subjects, and CRP levels increase within 6 hours after the onset of bacterial infection." (PMID 25888882, 2015). "Attempts at panel tests, including CRP combined with IL-18 because of its role in anti-viral immunity, have been unsuccessful in differentiating viral from bacterial infection." (PMID 26672961, 2015). "While the utility of increased CRP levels to suggest bacterial infections is well established, viral-induced proteins such as TRAIL are not used in clinical practice." (PMID 25785720, 2015). "Although various markers such as WBC count and CRP concentration are commonly used to identify bacterial infection, their validity is limited in kidney transplant recipients undergoing immunosuppressive therapy." (PMID 26275220, 2015). "The combination of either PCT or CRP alongside MxA would be helpful in differentiating viral from bacterial infection." (PMID 26672961, 2015). "In contrast PCT values were more discriminative than WBC and CRP in distinguishing a bacterial infection from another inflammatory process though it has low sensitivity." (PMID 26182343, 2015). "CRP is also an acute phase reactant that is suggested to be a marker of the presence of bacterial infection." (PMID 26498833, 2015). "In clinical practice, the diagnosis of a bacterial infection requiring antibiotic treatment is made from observation of clinical symptoms, supported by leukocyte counts and/or C-reactive protein (CRP) measurement." (PMID 26213499, 2015). "For CRP at a threshold of 10 mg/L, the sensitivity of detecting bacterial infections was 95 % with a specificity of 49 %." (PMID 26558692, 2015). "PCT, in particular, has been reported to be superior to endotoxin, β-D-glucan, IL-6, and C-reactive protein for differentiating between bacterial infections, including sepsis, and non-bacterial infections." (PMID 26623644, 2015).
bacterial infection (continued). "The value of CRP as a predictive marker for bacterial infection in neonates has been studied with varying results." (PMID 26259626, 2015). "For diagnosis of bacterial infection among preterm infants, the combination of IL-6 and CRP had a high sensitivity and specificity." (PMID 25894336, 2015). "AFOP can produce an elevated ESR and CRP; however a raised white cell count with striking neutrophilia is most suggestive of a simultaneous bacterial infection which also responded to antibiotic therapy." (PMID 25890084, 2015). "Current evidence suggests that serum procalcitonin is a specific marker of active bacterial infection, while CRP level denotes systemic inflammatory state." (PMID 26010741, 2015). "We only included children with symptoms of possible serious bacterial infection and elevated serum CRP concentration." (PMID 25909192, 2015). "Procalcitonin and C-reactive protein (CRP) are established biomarkers of bacterial infections, and are widely used in high income countries, particularly in hospital settings." (PMID 26558692, 2015). "Next, we compared the performance of the signature to that of procalcitonin and CRP, two proteins used in clinical practice to diagnose bacterial infections." (PMID 25785720, 2015). "Although several biomarkers are used to aid rapid identification of bacterial infection such as C-reactive protein (CRP), procalcitonin, and various interleukins, these markers have limitations in a lack of specificity or cost-effectiveness." (PMID 26275220, 2015). "Prospective studies have shown that CRP is also a valuable marker and is more sensitive than other markers like white cell count and absolute neutrophil count in predicting serious bacterial infection in febrile infants." (PMID 25909192, 2015). "PSBI was defined as signs/symptoms of possible serious bacterial infection along with baseline C-reactive protein(CRP) level >12mg/L." (PMID 25909192, 2015). "In the literature comparing procalcitonin and CRP as biomarkers of bacterial infection, procalcitonin was often found superior, particularly in critical care." (PMID 26558692, 2015). "RADT was not believed to be relevant since it detects only one bacterium, while CRP was considered as a reliable numerical measure of bacterial infection." (PMID 26141740, 2015). "At the time the patient was admitted, laboratory tests such as WBC, CRP often indicate an acute bacterial infection." (PMID 25524126, 2014). "As in other studies, our results showed a significant positive correlation between CRP and neutrophil levels in supporting of bacterial infection." (PMID 24764729, 2014). "Another interesting finding was the remarkable pathogen identification rate from blood in Group B. Both C-reactive protein and procalcitonin concentrations can suggest bacterial infection in emergency patients." (PMID 25259806, 2014). "Antibiotics should not be recommended in such cases with a normal neutrophil and IG levels and CRP value, even when bacterial infections is suspected clinically." (PMID 24764729, 2014). "Normal values for neutrophil, IG and CRP excluded bacterial infections had a 100% specificity and positive predictive value in a generic context." (PMID 24764729, 2014). "Elevated CRP and neutrophil levels were noted in only 27 of 67 patients with probable bacterial infections who were treated with antibiotics." (PMID 24764729, 2014). "Few data are available evaluating CRP for the detection of bacterial infections in children with fever." (PMID 24764729, 2014). "The positive correlation between suPAR and CRP concentrations was driven by the group of neonates with bacterial infections (rs = 0.52, P = 0.02)." (PMID 24882949, 2014). "A study of 151 patients (96 with bacterial infections) were evaluated with 6 biomarkers including sTREM-1, CRP, and PCT and found that a combination of the markers showed improved diagnostic ability compared with any single maker." (PMID 24772418, 2014).
bacterial infection (continued). "C-reactive protein (CRP) is also useful for assessment of young children with serious bacterial infections." (PMID 24764729, 2014). "The purpose of the study was to evaluate leukocyte populations and CRP level to predict bacterial infections in febrile outpatient children." (PMID 24764729, 2014). "At the time of diagnosis, patients with bacterial infections had increased serum CRP level, neutrophil, lymphocyte, and monocyte percent compared with the control group (p<0.05)." (PMID 24764729, 2014). "It is capable of interfering with the production of C-reactive protein, so it can be detected earlier than C-reactive protein during bacterial infection." (PMID 25614712, 2014). "In our patient population, PCT showed better discrimination than CRP for bacterial infection, albeit the difference was of borderline significance because of the small sample size." (PMID 24612487, 2014). "Serum IL‐27 was similar to CRP, a known biomarker of bacterial infection, in that levels of this gene product were increased during exacerbations associated with sputum purulence, itself a sign of bacterial involvement in exacerbation." (PMID 24994897, 2014). "C-reactive protein was significantly correlated with neutrophil level in bacterial infections (r: 0.76, p<0.05)." (PMID 24764729, 2014). "Our results have shown that normal neutrophil and IG levels and CRP value excluded bacterial infections with a predictive value of 100% in children presenting with fever." (PMID 24764729, 2014). "In multivariate analysis, CRP was a better indicator for bacterial infections with an odds ratio of 6.1 (95% CI, 1.5-24.6 )." (PMID 24764729, 2014). "The specificity of neutrophil and IG levels was higher for diagnosing bacterial infections than that of CRP alone." (PMID 24764729, 2014). "In the EP3OS guidelines, C-reactive protein measurements were briefly mentioned as helpful to exclude suspicion of a bacterial infection." (PMID 23659709, 2013). "Patients with TB and bacterial infection presented lower levels of CRP than patients with CMV disease." (PMID 24222903, 2013). "There are several studies which have used different cut off values for CRP ranging from 10–70 mg/L and have reported that the sensitivity of CRP for identifying serious bacterial infections (SBI) ranges from 63% to 95%, and specificity ranges from 40% to 91%." (PMID 23869218, 2013). "The elevations in the CRP and haptoglobin concentrations were also consistent with bacterial infection and an inflammatory state." (PMID 23936104, 2013). "Analyses of surrogate markers (fever, c-reactive protein and procalcitonin levels) for bacterial infection within the first week after symptom-onset revealed a high number of pathological results." (PMID 24069356, 2013). "On the other hand, in another review, PCT concentration was found to be better than CRP for diagnosis of bacterial infection." (PMID 23547830, 2013). "A majority of the febrile neutropenic patients with bacterial infections had significantly higher serum CRP levels." (PMID 23634180, 2013). "The time of increased CRP concentrations is consistent with the time course of bacterial infection and elevated cytokine concentrations." (PMID 24175013, 2013). "CRP is an acute-phase protein produced by the liver as part of the body’s inflammatory response to bacterial infection and tissue injury." (PMID 23941472, 2013). "In the patients with bacterial infections, IL-1Ra and IL-8 demonstrated positive correlation with C-reactive protein, whereas, IL-1Ra, TNF-α, and MCP-1 correlated with procalcitonin." (PMID 23690657, 2013). "In the past decade PCT was established as a surrogate marker for bacterial infection not only because of quicker metabolism than CRP but also for better specificity in detection of bacterial infection." (PMID 23766566, 2013). "CRP increases during a number of malignancies, connective tissue disorders and bacterial infections." (PMID 24288487, 2013).
bacterial infection (continued). "Early reports described a high prevalence of elevated CRP levels in infected infants, but levels are elevated in only 35% to 65% of neonates with bacterial infection at the onset of illness." (PMID 23941472, 2013). "Serum CRP levels of more than 40 mg/L have been shown to be suggestive and sensitive markers for bacterial infections in immunocompromised febrile patients." (PMID 23634180, 2013). "C-Reactive protein (CRP) is an acute-phase reactant, and CRP level measurements are frequently used to aid in the diagnosis of bacterial infections." (PMID 27029310, 2013). "Biological markers such as procalcitonin and CRP have been used in the diagnosis of bacterial infections." (PMID 23194114, 2012). "The combination of established inflammatory makers (WBC, CRP) combined with a biomarker of stress, i.e. copeptin or a biomarker of bacterial infection, i.e. PCT improves prediction of SAI compared to the strongest prognostic marker alone." (PMID 23118979, 2012). "In conclusion, routine CRP ordering for the detection of bacterial infection in sick children and neonates needs further scrutiny by practicing physicians." (PMID 22943554, 2012). "Along with ANC, CRP is a well-described marker for bacterial infection in neonates, children and adults." (PMID 23272177, 2012). "It is possible for even a newly graduated doctor to make decisions about antibiotic treatment for the majority of cases suspected for a bacterial infection with a confirmatory CRP result." (PMID 21906396, 2011). "As markers for inflammation and bacterial infection in clinical routine, CRP and PCT reached AUC statistics of 0.524/0.531 and 0.545/0.550." (PMID 21324198, 2011). "Exclusion of patients with CRP values above 40 mg/L, which likely reflect bacterial infection, resulted in similar hazard ratios for all endpoints (data not shown)." (PMID 21639875, 2011). "They found that combination of IL-8 and C-reactive protein (CRP) is able to detect culture proven nasocomial bacterial infection with 96% specificity." (PMID 20550702, 2010). "When these pitfalls are taken into account, PCT performs better than CRP in diagnosing neonatal bacterial infection." (PMID 21143869, 2010). "C reactive protein (CRP) is a component of the innate immune system and increased levels of CRP are observed early in response to severe bacterial infection." (PMID 20398379, 2010). "The high serum CRP levels that were observed among some of the patients in our series are usually found among patients with bacterial infections." (PMID 20920320, 2010). "CRP is consistently found in bacterial infection, acute rheumatic fever, and malignant diseases, viral infections, tuberculosis, and also in patients following surgical operations and blood transfusions." (PMID 20407653, 2009). "Admission PCT and CRP are useful markers of invasive bacterial infection in severely ill African children." (PMID 19675669, 2009). "Among patients with plasma CRP concentrations higher than 10 mg/dl, 80 to 85% have bacterial infections, according to previous studies." (PMID 20512289, 2009). "CRP is an acute-phase reactant, and CRP level measurements are frequently used to aid in the diagnosis of bacterial infections." (PMID 19578505, 2008). "A "normal" CRP-concentration in these conditions can therefore be considered a false negative test result if CRP should be regarded as an indicator of bacterial infection." (PMID 18706087, 2008). "Among patients with plasma CRP concentrations higher than 10 mg/dL, 80-to-85percent have bacterial infections." (PMID 18385816, 2008). "C-reactive protein (CRP) is an indicator of inflammation, and is often used in the diagnosis of bacterial infections." (PMID 18706087, 2008). "The last meta-analysis established that PCT is a more sensitive and specific parameter for the evidence of systemic bacterial infection than C-reactive protein (CRP)." (PMID 18088403, 2007).
bacterial infection (continued). "PCT levels were similar in patients who received aprotinin compared with the control group.PCT levels were less than 0.5 ng/ml at all time points but were higher in bacterial infection versus SIRS.CRP levels were similar in bacterial infection and SIRS." (PMID 17038199, 2006). "Most studies support the observation that children with bacterial infections have higher levels of CRP and procalcitonin than those with viral infections." (PMID 15736995, 2005). "However, CRP exhibits slow kinetics and low specificity for bacterial infections, making it unsuitable as an early marker of postoperative infectious complications." (PMID 41334533, 2026). "This aligns with previous data linking GDF‐15 to LPS and CRP levels in patients with alcohol‐associated hepatitis, as well as experimental data showing GDF‐15 upregulation following LPS injection in mice, mimicking bacterial infections." (PMID 41555670, 2026). "Studies have shown that CRP rises significantly during bacterial infections, aiding in distinguishing TBM from BM, which could be why CRP in our paper was higher in the non-TBM group than in the TBM group." (PMID 41313026, 2026). "CRP tests, in particular, help distinguish between viral and bacterial infections by indicating the level of inflammation, which can influence decisions like whether to refer a patient to the hospital or manage them in primary care." (PMID 40921638, 2025). "CRP and cortisol are early indicators of bacterial infection in DKA patients." (PMID 39946377, 2025). "CRP was an accurate predictor of early bacterial infection in DKA." (PMID 39946377, 2025). "PCT, a sensitive inflammatory marker, surpasses CRP in detecting bacterial infections." (PMID 40122698, 2025). "Similarly, IL-6 induces rapid SAA1 synthesis, which is a more sensitive early marker of bacterial infection than CRP, often increasing over 1000-fold." (PMID 40572197, 2025). "It is already commonly known that CRP is less specific than PCT in bacterial infections." (PMID 40046054, 2025). "Inflammatory markers other than CRP, such as procalcitonin, may be useful for predicting bacterial infections and guiding appropriate antibiotic use." (PMID 41153485, 2025). "Human CRP is present at a trace level in healthy individuals, but rapidly rises by as much as 1000 folds during severe bacterial infections and other inflammatory conditions, making it a common biomarker for clinical diagnosis of systemic infections and inflammation." (PMID 41214213, 2025). "Among ED patients, CRP levels tend to rise in the setting of bacterial infection." (PMID 40993724, 2025). "Moreover, CRP is crucial for the synthesis of cytokines, in addition to facilitating phagocytosis and nitric oxide production in response to bacterial infection." (PMID 41383965, 2025). "The predictive value of cortisol was comparable to that of CRP in predicting bacterial infection." (PMID 39946377, 2025). "Although the 2 groups differed significantly in the described characteristics, both had radiologically confirmed CAAP and had abnormally high mean CRP, white blood cell count and neutrophil count values, and mean temperature on admission, suggesting that most had bacterial infections." (PMID 41346443, 2025). "However, in our study, CRP outperformed PCT in distinguishing viral from bacterial infections (AUC: 0.7893 vs. 0.6088)." (PMID 40046054, 2025). "The almost universal negativity of procalcitonin, even in cases with very high levels of CRP, fever and neutrophil leucocytosis, is consistent with the absence of underlying bacterial infections, helping clinicians in avoiding antibiotics escalation." (PMID 39798014, 2025). "However, if clinical decision-making strongly relied on CRP values, many AdV infections would be misclassified as bacterial infections and managed accordingly." (PMID 40506878, 2025). "However, the predictive value of CRP and IL-6 in differentiating bacterial infections among patients with DKA has yet to be investigated." (PMID 39946377, 2025).